BRAF (B-Raf proto-oncogene, serine/threonine kinase)
Diseases named in the same sentence as BRAF in open-access papers (continued):
Sharing a sentence is not in itself a finding about the gene and the disease.
melanoma (continued). "Firstly, these inhibitors promote the creation of an immune-stimulating environment within BRAF-mutant melanomas." (PMID 38021761, 2023). "To explore how RAB6B and RAB27A levels affect HMGCR inhibitor sensitivity, we analyzed differential mass spectrometric-based proteome profiles of parental and chronic BRAF-inhibitor treated melanoma cells." (PMID 37277330, 2023). "This real‐world study was conducted to assess the association of BRAF, NRAS, or KIT mutations with outcome in melanoma receiving adjuvant anti‐PD‐1 monotherapy." (PMID 37403699, 2023). "The NCI-MATCH trial included patients with BRAF V600E-positive solid tumours (excluding melanoma, thyroid carcinoma and colorectal carcinoma), while the paediatric trial included patients with refractory or recurrent low or high grade glioma." (PMID 37542343, 2023). "Clinical studies showed safety and efficacy of BRAF inhibitor therapy in patients with treated and untreated melanoma brain metastases more recently." (PMID 37920169, 2023). "Our data suggest that VEGFA/BRAF targeting in melanoma induces the activation of innate and adaptive immunity and prepares tumors for ICB." (PMID 37183363, 2023). "Somatic mutations in BRAF, NRAS, or neurofibromatosis 1 (NF1) are frequently observed in melanoma and their frequencies have been shown to depend on the cumulative amount of UV light and the anatomical site." (PMID 37658191, 2023). "One example is melanoma lines that contain the microRNA known as miRNA-125a, which promotes resistance to BRAF inhibitors and thus suppresses the intrinsic pathway of apoptosis in these cells." (PMID 37445615, 2023). "Because there is an outstanding clinical need to identify novel and exploitable vulnerabilities that arise within treated BRAF-inhibitor resistant melanomas, we performed a cell-based growth inhibitory chemical screen." (PMID 37277330, 2023). "In the presence of mutant-BRAF, PTEN-deficient melanoma cells express constitutively active Akt3, which protects against apoptosis by upregulating Bim and Bmf." (PMID 37181747, 2023). "Nowadays, planned, published and ongoing trials include combinations of RTK inhibition with other treatment modalities underlining the importance of finding efficient treatments for non-BRAF mutant melanoma patients." (PMID 37215708, 2023). "In one study, two BRAF mutant melanoma cell lines that were made resistant to BRAF inhibitor PLX4720 exhibited increased dependency on oxphos." (PMID 37779896, 2023). "Non-BRAF mutant melanoma patients have limited treatment options with only 30% responding to tyrosine kinase (TK) inhibitors against growth factor receptors." (PMID 37215708, 2023). "Whipple and Brinckerhoff demonstrated that BRAF V600E melanoma cells secrete factors that interact with stromal fibroblasts and enhance tumourigenicity." (PMID 37627054, 2023). "Discovery of the oncogenic capacity of BRAF spurred the development of RAF inhibitors, with proven clinical benefit in BRAF aberrant melanoma, colorectal cancer, NSCLC, and papillary thyroid carcinoma." (PMID 37124503, 2023). "Encorafenib is akinase inhibitor indicated for the treatment ofpatients with BRAF mutant melanoma and BRAF mutant metastatic colorectalcancer." (PMID 37037186, 2023). "Another type of genetic rearrangement commonly observed in melanomas is BRAF gene fusions, which have been detected in 3-6% of patients and are more frequent in young women with certain histopathological subtypes." (PMID 37627054, 2023). "CNV analysis of melanoma driver genes showed that median CNV frequency was 2.6 times higher in BRAF V600+ NR than in BRAF V600+ R samples." (PMID 36901733, 2023). "BRAF(V600E) melanoma cells expressed higher levels of these cytokines and of MMP-1 than wild-type counterparts and a specific inhibitor of the MAPK pathway, vemurafenib abrogates this condition." (PMID 37762344, 2023).
melanoma (continued). "Studies have pinpointed elevated CRAF protein levels in melanoma cell culture models as a potential mechanism for BRAF inhibitor resistance." (PMID 38111008, 2023). "The natural history of BRAF and NRAS mutant melanoma suggests an increased risk of progression and increased frequency of metastatic disease, including an increased frequency of brain metastases." (PMID 37444637, 2023). "As already seen in the normalized data, MALAT1 expression was significantly decreased in BRAF- and NRAS-mutated melanoma (13.5-fold, p < 0.001), LIHC (3.3-fold, p < 0.001) and LUSC (8.7-fold, p < 0.001), when compared to their corresponding healthy tissue." (PMID 37235843, 2023). "BRAF inhibitors (BRAFi) are currently approved for BRAF V600E and V600K mutant melanoma and successfully improved the progression-free survival and overall survival of patients with these mutations." (PMID 37239381, 2023). "Treatments with combined selected BRAF inhibitors and mitogen-activated protein kinase inhibitors have significantly improved response and overall survival in patients with BRAF V600-mutant melanoma." (PMID 36704723, 2023). "Specifically, evidence demonstrated that increased levels of the mRNA were found in BRAF mutant melanomas with high phosphor-Erk levels." (PMID 36649032, 2023). "Classification models showed molecular differences between BRAF and NRAS mutated melanoma, and identification of both was possible with an accuracy of 87–89% and 76–79%, depending on the respective classification method applied." (PMID 36982192, 2023). "Approximately, 70% of melanoma have activating mutations in the MAPK pathway, two thirds of which in the BRAF gene and are thus targetable by BRAF inhibitors (BRAFi) including vemurafenib, dabrafenib and encorafenib." (PMID 36988735, 2023). "In patients with BRAF mutant melanoma, the combination of BRAFi and MEKi has shown improvements in median OS from 6–9 to 22–33 months." (PMID 36967556, 2023). "The patients in our cohort with BRAF‐mutant melanoma were heavily pre‐treated, all with BRAF inhibitors and some with prior chemotherapy or ipilimumab." (PMID 36404632, 2023). "Upregulation of Bim and Puma was also reported in melanoma cells in response to BRAF inhibition, which is explained by the suppression of these proteins through active MAPK pathways." (PMID 36902392, 2023). "A classification based on BRAF mutation status and TMB is proposed to predict RFS in melanoma patients with adjuvant anti-PD-1 therapy." (PMID 35192052, 2023). "Using gene expression profiling, we aimed to study the components of the PI3K/AKT/mTOR pathway, which is involved in resistance development in BRAF-mutant melanomas." (PMID 37895015, 2023). "Comorbidities and geographical region play a role in deciding the adjuvant treatment of choice in resected stage III BRAF-mutant melanoma patients in the Netherlands." (PMID 36672358, 2023). "Our studies in melanoma tumors suggested that BRAF/VEGFA targeting reshaped the TME, leading to an improvement of anti‐PD‐1 effectiveness and inducing an immunologic memory response able to reject a second tumor." (PMID 37183363, 2023). "A recent study illustrated that healthy aged dermal fibroblasts facilitated increased resistance to targeted BRAF therapy in allogeneic mouse models of melanoma by secreting SFRP2 into the TME." (PMID 36945046, 2023). "Since BRAF gene mutations, which are a component of the RAF/MEK/ERK pathway, are commonly found in melanoma and papillary thyroid cancer, few studies have investigated its presence in PA." (PMID 37446128, 2023). "Most data about disease response following discontinuation of BRAFi therapy are derived from adults with BRAF V600–mutant melanoma." (PMID 37124503, 2023).
melanoma (continued). "The second are drugs targeted against key protein kinases in melanoma pathogenesis, such as BRAF and MEK." (PMID 37627116, 2023). "Here, we show that upon Yes-associated protein 1 (YAP1) ablation in cancer-associated fibroblasts (CAFs), the progression of a BRAF-mutant mouse melanoma was significantly suppressed in vivo, and overexpressing YAP1 in CAFs accelerated melanoma growth." (PMID 37546745, 2023). "To determine if the impact of mtRNA-driven, tumor cell autonomous Type I IFN production is sufficient to elicit an anti-tumor immune response in vivo, we turned to the classically immunologically cold B16 (BRAF wild type) melanoma model." (PMID 36918588, 2023). "Survival analysis and receiver operating characteristic (ROC) curve evaluation in both cohorts with BRAF V600E WT and BRAF V600E-mutant melanoma showed an accurate prognostic estimation of ICD-related risk signature." (PMID 36704723, 2023). "It is highly related to high mortality in patients with PTC or melanoma, which also stimulates research on BRAF inhibitors." (PMID 36331719, 2023). "In summary, the combined inhibition of EZH2 and BRAF improves anti-cancer effects through enhanced cell-cycle arrest and the increased cell death of melanoma cells resistant to vemurafenib." (PMID 36768289, 2023). "Taking BRAF-mutant melanoma as paradigm, we previously identified the lipogenic regulator SREBP-1 as a central mediator of resistance to MAPK-targeted therapy." (PMID 37072838, 2023). "Amongst the constituents of the MAPK pathway, BRAF is a critical player in the regulation of the cascade, and it is most prominently dysregulated in melanoma." (PMID 36967556, 2023). "Melanomas that have acquired resistance to BRAF plus MEK inhibition are often characterized by rapidly progressing disease." (PMID 37370834, 2023). "This offers potential for a new treatment strategy based on targeting VEGFA that aims to overcome resistance to BRAF blockade in melanoma." (PMID 37183363, 2023). "In the BRAF V600E mutant melanoma, the result further confirmed that poor OS was correlated with a high-risk score." (PMID 36704723, 2023). "Continuous versus intermittent BRAF and MEK inhibition in melanoma patients with BRAFV600E/K mutations was tested in a randomized, open-label phase 2 clinical trial (NCT02196181)." (PMID 37370689, 2023). "Our results suggest evaluating DDIs in the clinical practice of melanoma patients treated with BRAF/MEK inhibitors to reduce potentially avoidable toxicities and improve treatment tolerability and patients’ quality of life." (PMID 37760556, 2023). "Among these mutations, BRAF and NRAS are two of the most common, but also mutually exclusively mutated, oncogenes recognised in melanoma." (PMID 37627054, 2023). "Further, conditioned medium from the BRAF(V600E) melanoma cells promoted the activation of stromal fibroblasts, an event partially attributable to IL1α/β-mediated modulation of PD-1 ligands in melanoma CAFs." (PMID 37762344, 2023). "The primary endpoint was the ORR in BRAF wild-type melanomas, with OS being an exploratory endpoint." (PMID 37404764, 2023). "To facilitate preclinical studies of combination therapies to provide durable responses, we describe the first mouse melanoma lines resistant to BRAF inhibitors." (PMID 37762086, 2023). "A metabolism-centered pharmacological screen further identifies statins (HMGCR inhibitors) as a collateral vulnerability within PGC1α-suppressed BRAF-inhibitor resistant melanomas." (PMID 37277330, 2023). "According to the ASCO guidelines on systemic treatment of melanoma, patients with BRAF-mutant melanoma stage III should be treated with either nivolumab, pembrolizumab or a combination dabrafenib and trametinib therapy." (PMID 36865793, 2023). "Overall, we provide a promising leading compound for BRAF V600E or RAS mutant melanoma and colorectal cancer through dual targeting of CRAF and MEK1/2." (PMID 36872366, 2023).
melanoma (continued). "While targeted treatment against BRAF(V600E) improve survival for melanoma patients, many will see their cancer recur." (PMID 37277330, 2023). "In BRAF-positive melanoma, Anti-PD-L1 atezolizumab in combination with the BRAF-MEK inhibitor vemurafenib + cobimetinib provided a survival advantage compared to placebo with the same combination of target therapy." (PMID 37568785, 2023). "PanDrugs2 results showed as BTCs: RAF inhibitors (e.g. vemurafenib) and MEK inhibitors (e.g. trametinib), which are FDA approved drugs, alone or in combination, for the treatment of BRAF-mutant melanoma patients." (PMID 37207338, 2023). "Later COMBI‐AD trial demonstrated dual‐targeted therapy of Dabrafenib plus Trametinib (D + T) significantly reduced the risks of recurrence and metastasis for Stage III BRAF‐mutant melanoma." (PMID 37016119, 2023). "Tunlametinib also demonstrated stronger inhibition of BRAF-mutant melanoma and colorectal xenograft when compared to MEK162." (PMID 37808191, 2023). "Using a panel of melanoma cell lines (BRAF inhibitor-sensitive (A375P, SKMEL5, MEL1617) or BRAF inhibitor-resistant (MEL1617R, WM983BR, MEL624)), these investigators studied the possible relationship between autophagy and vemurafenib both in vitro and in vivo." (PMID 37834222, 2023). "It is noteworthy that clinical sample analyses have revealed the emergence of secondary benign and malignant skin tumors in BRAFV600E melanoma patients undergoing BRAF inhibitor therapy." (PMID 38111008, 2023). "In BRAF mutant melanoma, MAPK pathway blockade combined with immune checkpoint inhibitor therapy yields durable clinical benefit." (PMID 37302081, 2023). "Adjuvant BRAF/MEK- and anti-PD-1 inhibition have significantly improved recurrence-free survival (RFS) compared to placebo in resected stage III BRAF-mutant melanoma." (PMID 36672358, 2023). "BRAF is one of the genes upregulated in melanoma cells, and inhibition of BRAF signaling has been a top target for therapy." (PMID 37233647, 2023). "The combination of dabrafenib plus trametinib represents standard of care for BRAF-V600E-mutant melanoma and lung cancer patients and was applied in case of BRAF-V600E mutation on the basis of several case reports in brain tumors." (PMID 35953681, 2023). "Treatment with BRAF inhibitors achieved a 20% of ORR and 70% disease control rate (DCR) in a small cohort of 12 MM patients with metastatic or unresectable BRAF V600E-mutant melanoma." (PMID 36900152, 2023). "C/EBPβ has also been studied in different cancers and has, for instance, been associated with a decrease in cell proliferation and partial reduction in BRAF-inhibitor resistance in malignant melanoma." (PMID 36675048, 2023). "In vitro studies have demonstrated that MEKi in BRAF-mutant melanoma induces cytotoxic autophagy, followed by the emergence of CD271-expressing subpopulations." (PMID 37189846, 2023). "This case report has some limitations, such as we have been unable to incorporate the BRAF status of the primary cervical melanoma in this case report due to unavailability of molecular testing and epigenetic profiling of malignant melanoma in Uganda." (PMID 38104134, 2023). "These ‘nevi and melanoma’ genes include BRAF, CDKN2A, MITF, some telomere length maintenance genes, and IRF4." (PMID 36834954, 2023). "Follow-up studies on melanoma cells resistant to both a BRAF inhibitor (encorafenib) and an MEK inhibitor (binimetinib) found that OPN was one of several genes whose expression was unaltered during a drug “holiday”." (PMID 37444590, 2023). "RAS-targeting siRNA has been shown to sensitize melanoma cells in vitro to BRAF inhibitors, though it has had limited applications in vivo to date." (PMID 37370834, 2023). "For treatment of melanoma with targeted BRAF inhibitors, adaptive mechanisms have been suggested to involve metabolic changes, such as increased dependency on lipid metabolism." (PMID 37277330, 2023).
melanoma (continued). "BRAF mutated patients had significantly higher expression of APRIL/TNFSF13 and CXCL10 in comparison to BRAF wild-type patients, while NRAS wild-type patients had higher expression of TNFSF13 in comparison to patients with melanomas harboring NRAS mutations." (PMID 37435077, 2023). "Second, we predefined appropriate frontline treatment to reflect the current standard of care and most advances in the treatment of BRAF-mutant melanoma." (PMID 36653848, 2023). "For melanoma, it has been widely used to study the effects of BRAF or NRAS (key initiating events in melanoma) and has uncovered important developmental and microenvironmental influences on these tumors." (PMID 36472402, 2023). "The various levels of mutation have been seen in multiple cancers including melanoma, NSCLC, papillary thyroid cancer and colorectal cancer and around 300 distinct BRAF mutations have been identified." (PMID 37645429, 2023). "In the pembrolizumab arms, the median PFS was 3.8 months in BRAF wild-type melanoma patients versus 2.8 months in BRAF-mutant melanoma patients; the 6-month PFS rate was 40.9% versus 19.5%, with an ORR of 26.7% vs. 11.9%, respectively." (PMID 36995534, 2023). "In this multi‐center real‐world data study, we analyzed the clinical efficacy of first‐line BRAF/MEKi, Anti‐PD‐1, and PD‐1/CTLA‐4 therapies in 336 Asian patients with advanced BRAF V600‐mutant melanoma." (PMID 37584204, 2023). "In the context of melanoma, applied AI models have confirmed the validity of predictor variables of brain metastases, such as BRAF status, to predict response to treatment." (PMID 36900136, 2023). "Factors which are driving melanoma drug resistance mainly involve mutations in the mitogen-activated protein kinase (MAPK) pathway, e.g., BRAF splice variants, neuroblastoma RAS viral oncogene homolog (NRAS) amplification or parallel survival pathways." (PMID 37509693, 2023). "In the final dose cohort, 2/6 patients with refractory BRAF wild-type melanoma had a close to complete response, and prolonged stable disease." (PMID 36831202, 2023). "Another group compared the Idylla assay with anti-BRAF V600E (clone VE1) immunohistochemistry in 90 melanoma samples." (PMID 37174112, 2023). "This study aimed to assess the efficacy of first‐line BRAF/MEKi, Anti‐PD‐1, and PD‐1/CTLA‐4 in Asian patients with advanced BRAF V600‐mutant melanoma in a real‐world setting." (PMID 37584204, 2023). "In the same way, the expression of miR-146a-5p is correlated with the sensitivity of melanoma to BRAF inhibitors." (PMID 37174072, 2023). "While BRAF-targeted therapy is highly effective for melanoma, it is often ineffective against other cancers." (PMID 38136350, 2023). "Our results showed that MALAT1-ASO treatment decreased BRAF RNA expression and protein levels, and MALAT1 had increased correlation with MAPK-pathway associated genes in melanoma patient samples compared to healthy skin." (PMID 37235843, 2023). "According to the current guidelines, BRAF-wildtype patients with advanced melanoma should either receive a dual therapy with ipilimumab plus nivolumab or a monotherapy with nivolumab or pembrolizumab (PDL-1 inhibitor), on the basis of clinical discretion." (PMID 36835424, 2023). "The current therapeutic scenario for patients with BRAF-mutant melanoma has been extensively described." (PMID 36901733, 2023). "In a phase 1 dose-escalation clinical trial, a partial response was observed in a patient with V600E BRAF-mutant melanoma and in a patient with platinum-refractory epithelial ovarian cancer, exhibiting PTEN loss and PIK3CA amplification." (PMID 36765661, 2023). "BRAF-mutant melanoma patients benefit from the combinatorial treatments with BRAF and MEK inhibitors." (PMID 38008717, 2023). "Collectively these data suggest that the aggressive melanoma phenotypic traits were dependent on PPARGC1A suppression as a result of chronic BRAF inhibitor treatment, which is consistent with our prior studies." (PMID 37277330, 2023).